APOBEC3B (apolipoprotein B mRNA editing enzyme catalytic subunit 3B)
Description:
DNA deaminase (cytidine deaminase) which acts as an inhibitor of retrovirus replication and retrotransposon mobility via deaminase-dependent and -independent mechanisms. After the penetration of retroviral nucleocapsids into target cells of infection and the initiation of reverse transcription, it can induce the conversion of cytosine to uracil in the minus-sense single-strand viral DNA, leading to G-to-A hypermutations in the subsequent plus-strand viral DNA. The resultant detrimental levels of mutations in the proviral genome, along with a deamination-independent mechanism that works prior to the proviral integration, together exert efficient antiretroviral effects in infected target cells. Selectively targets single-stranded DNA and does not deaminate double-stranded DNA or single- or double-stranded RNA. Exhibits antiviral activity against simian immunodeficiency virus (SIV), hepatitis B virus (HBV) and human T-cell leukemia virus type 1 (HTLV-1) and may inhibit the mobility of LTR and non-LTR retrotransposons.
Synonyms: A3B; PHRBNL; FLJ21201; APOBEC1L; ARCD3; ARP4; DJ742C19.2; bK150C2.2
Tractability: Small molecule: a structure with a bound ligand is known. PROTAC: ubiquitination databases record sites on it.
Target class: Enzyme; Hydrolase
Gene: Protein-coding gene on chromosome 22 (38,982,347 to 38,992,804, forward strand). Ensembl gene ENSG00000179750.
Subcellular location: Nucleus
Subcellular location (Human Protein Atlas): Nucleoplasm
Pathways (Reactome):
Metabolism of RNA: Formation of the Editosome; mRNA Editing: C to U Conversion
Gene Ontology:
Molecular function: cytidine deaminase activity; protein binding; RNA binding; hydrolase activity; zinc ion binding
Biological process: clearance of foreign intracellular DNA; defense response to virus; transposable element silencing; cytidine to uridine editing; DNA cytosine deamination; negative regulation of single stranded viral RNA replication via double stranded DNA intermediate
Cellular component: nucleoplasm; nucleus; cytoplasm; P-body
Genetic constraint (gnomAD): Loss-of-function variants: 31 observed, 49 expected, observed/expected ratio (o/e) 0.63, 90% interval 0.47 to 0.85. The synonymous counts are far from expectation, so gnomAD's model fits this gene poorly and the ratio says little. Missense variants: 347 observed, 458.76 expected, observed/expected ratio (o/e) 0.76, 90% interval 0.69 to 0.83. Synonymous variants: 132 observed, 170.4 expected, observed/expected ratio (o/e) 0.77, 90% interval 0.67 to 0.89.
Cancer hallmarks: genome instability and mutations (promotes); tumour promoting inflammation (promotes); genome instability and mutations (suppresses)
Homologues: Orthologues: macaque APOBEC3B (84% identical), chimpanzee APOBEC3B (82% identical), macaque APOBEC3A (41% identical). Paralogues in human: APOBEC3D (60% identical), APOBEC3F (59% identical), APOBEC3G (57% identical), APOBEC3A (45% identical), APOBEC3C (21% identical), AICDA (20% identical), APOBEC2 (16% identical), APOBEC3H (16% identical), APOBEC1 (14% identical).
Diseases named in the same sentence as APOBEC3B in open-access papers:
APOBEC3B is named in the same sentence as 116 diseases in open-access papers, as found by Europe PMC text mining. Sharing a sentence is not in itself a finding about the gene and the disease. The quoted sentences say what the papers report.
breast cancer (95 papers, 2013 to 2026). A primary or metastatic malignant neoplasm involving the breast. "According to the findings of M.B. Burns and colleagues, a potential source of these mutations in breast cancer is the cytidine deaminase APOBEC3B DNA." (PMID 41602431, 2026). "APOBEC enzymes, including APOBEC3B (A3B), have been linked to recurrent mutational patterns in breast cancers (BC)." (PMID 41366803, 2025). "It was shown that APOBEC3B expression is associated with poor prognosis for breast cancer and some other cancers." (PMID 41373684, 2025). "For example, studies in breast cancer report that high APOBEC3B expression is associated with more tumor infiltrating lymphocytes." (PMID 41373684, 2025). "Rs1014971 has also been associated with an increased cancer risk and the APOBEC3B expression in breast cancer." (PMID 38254863, 2024). "HPV infections upregulate and lead to mutations in APOBEC3B which increase the risk of breast cancer." (PMID 39187871, 2024). "APOBEC3B (A3B), another family member, has gained attention for its potential role in generating genomic DNA mutations in breast cancer." (PMID 39322638, 2024). "APOBEC3B has been demonstrated to induce somatic mutations in several types of malignancies, including breast cancer." (PMID 37510234, 2023). "A large deletion of APOBEC3B was associated with increased breast cancer risk, but the evidence is inconclusive." (PMID 37510234, 2023). "Based on our study there is insufficient evidence that the APOBEC3B p.Val262Phefs truncating mutation predisposes to breast cancer." (PMID 37510234, 2023). "It is unlikely that germline APOBEC3B mutations confer a clinically important risk of breast cancer (and probably other cancers)." (PMID 37510234, 2023). "In a pan-cancer analysis, high APOBEC3B expression was associated with increased immune activation in cutaneous melanoma and breast cancer." (PMID 36978147, 2023). "We identified a truncating mutation in four of 617 women (0.61%) with hereditary breast cancer by sequencing the entire APOBEC3B gene." (PMID 37510234, 2023). "Previously, hypermutation of COSMIC signatures 2 and 13 in breast cancer has been associated with the deletion polymorphism affecting the APOBEC3B locus, especially in ER+ breast cancer." (PMID 37974533, 2023). "In this study, we approached the question if APOBEC3B mutations predispose women to breast cancer in several ways, including the sequencing of the entire APOBEC3B gene in familial cases, and conducted a large case–control study and a pedigree analysis." (PMID 37510234, 2023). "APOBEC3B has been described as a strong driver of breast cancer and associated with aggressive clinical and pathological features." (PMID 35893033, 2022). "In humans, inactivating mutations and deletions in APOBEC3B appear to play a role in breast cancer development." (PMID 35458452, 2022). "In breast cancer, expression of APOBEC3B is increased and associated with mutation load and poor outcome, while high APOBEC3C-H expression was linked to favorable prognostic benefit for both cancer progression and mortality." (PMID 35817785, 2022). "It was found that APOBEC3B (A3B) is an important source of genomic mutations in a variety of human cancers, including breast cancer, head and neck cancer, cervical cancer, bladder cancer, lung cancer, and ovarian cancer." (PMID 36249021, 2022). "After viral DNA integration, mutations in APOBEC3B can lead to host genome instability and then to breast cancer progression." (PMID 34108009, 2021). "The mutation signature mediated by a consensus sequence of 4 (GTCA) nucleotides suggests the involvement of APOBEC3B, a well-known mutagenic enzyme associated with breast cancer and upregulated by doxorubicin." (PMID 33121045, 2020).
breast cancer (continued). "Previous studies have shown an association between APOBEC3B expression level and aggressive clinicopathologic characteristics and its expression is highly correlated with cellular proliferation in breast cancer." (PMID 32934779, 2020). "APOBEC3B (A3B)-catalyzed DNA cytosine deamination contributes to the overall mutational landscape in breast cancer." (PMID 32985974, 2020). "According to a recent comprehensive genome sequence analysis, a characteristic kataegis mutation pattern is prevalent in breast cancer, the generation of which is likely to involve APOBEC3B." (PMID 32880638, 2020). "Studies have reported that higher levels of APOBEC3B expression is associated with decreased survival rates among estrogen receptor-positive (ER+) breast cancer patients." (PMID 29853799, 2018). "Inactivating mutations and deletions in APOBEC3B are also thought to play a role in breast cancer development." (PMID 29404275, 2018). "Next, we evaluated the association between APOBEC3B and pCR when stratified by each breast cancer subtype." (PMID 30093965, 2018). "Clinical studies and an analysis of murine xenograft models found an association of increased APOBEC3B mRNA expression levels with tamoxifen resistance in estrogen receptor-positive (ER+) breast cancer." (PMID 29642934, 2018). "Although an association between APOBEC3B expression in breast cancer cells and sensitivity to another CHK1 inhibitor, CCT244747, was previously reported, that agent was absent from both the CCLE and the GDSC drug sensitivity data sets." (PMID 29642934, 2018). "Breast cancer associated CNVs overlapping with the genes APOBEC3B, GSTM1 and FGFR2 were validated using the TaqMan assay." (PMID 29116104, 2017). "In line with this, we previously reported an association between high APOBEC3B mRNA expression and poor outcome in a large cohort of patients with ERα-positive breast cancer." (PMID 28141868, 2017). "It was concluded that in the Caucasian population, the relationship of the APOBEC3B deletion with increased breast cancer risk cannot be convincingly stated; therefore, further large-scale comprehensive association studies are necessary." (PMID 29100317, 2017). "Our association study comprised 2972 cases and 3682 controls; it was the largest APOBEC3B deletion association study performed in European populations and the first APOBEC3B deletion association study to use the familial form of breast cancer." (PMID 29100317, 2017). "The currently available results report risk related to the APOBEC3B deletion in groups of unselected breast cancer cases." (PMID 29100317, 2017). "The role of the APOBEC3B deletion in familial breast cancer predisposition remains to be elucidated." (PMID 29100317, 2017). "In contrast, association of the APOBEC3B deletion with breast cancer is much less conclusive in European populations." (PMID 29100317, 2017). "In this study, we also identified CNVs showing a deletion in the APOBEC3B gene and associated with breast cancer risk." (PMID 29116104, 2017). "Previous studies reported an association between APOBEC3B expression and aggressive characteristics of the primary breast cancer, including high histologic grade, genomic grade, advanced stage, negative ERα status and HER2/ERBB2 amplification." (PMID 28141868, 2017).
breast cancer (continued). "In this study, we determined the prevalence of germline APOBEC3B deletion and its association with breast cancer risk in a cross-sectional hospital-based Asian multi-ethnic cohort of 1451 cases and 1442 controls from Malaysia." (PMID 27233495, 2016). "Several recent studies have implicated increased levels of the enzyme APOBEC3B in oestrogen receptor–positive breast cancer with poor patient outcomes." (PMID 26913069, 2016). "Next, we evaluated the association between the APOBEC3B copy number status and the clinicopathological variables of the 1,756 breast cancer patients." (PMID 27552096, 2016). "We found germline APOBEC3B deletion was associated with breast cancer risk, with ORs of 1.23 [95 % Cl: 1.05, 1.44] for one-copy deletion and 1.38 [95 % Cl: 1.10, 1.74] for two-copy deletion (P = 0.005) compared to women with no deletion." (PMID 27233495, 2016). "The association between APOBEC3B copy number and the response to treatment in breast cancer patients that received either first-line tamoxifen or chemotherapy for recurrent disease was also evaluated." (PMID 27552096, 2016). "APOBEC3B mRNA expression was found to be upregulated in most breast cancers and tumors expressing high levels of APOBEC3B had a 2-fold increase in mutations compared with tumors expressing low APOBEC3B levels." (PMID 27552096, 2016). "In this study, we demonstrated that high expression of APOBEC3B mRNA was significantly associated with aggressive phenotypes of breast cancer and poor RFS." (PMID 27977754, 2016). "In this study, we showed that germline APOBEC3B deletion is associated with an increased risk to breast cancer among Chinese, Malay and Indian women in Malaysia." (PMID 27233495, 2016). "In terms of breast cancer subtype, high APOBEC3B mRNA expression was significantly associated with the triple negative (TN) subtype." (PMID 27977754, 2016). "Association of APOBEC3B copy number status with clinicopathological variables in 1,756 primary breast cancers." (PMID 27552096, 2016). "Our breast cancer association results are consistent with previous findings in East Asian and Caucasian women, which implicate germline APOBEC3B deletion as a susceptibility factor for breast cancer by conferring carriers a modest risk to the disease." (PMID 27233495, 2016). "At the same time, the 29.5 kb deletion polymorphism of APOBEC3B was found to be associated with the increased breast cancer risk in different populations, although these findings were not confirmed in a Swedish study." (PMID 27552096, 2016). "Analysis of breast cancers from The Cancer Genome Atlas (TCGA) showed that germline APOBEC3B deletion is associated with an OR of 2.68 for one-copy deletion, and an OR of 3.82 for two-copy deletion with tumours that have a hypermutator phenotype." (PMID 27233495, 2016). "Invasive breast cancers have a high load of APOBEC3B-dependent mutations with a typical TpC dinucleotide signature, suggesting a derailed APOBEC activity during tumourigenesis." (PMID 26926109, 2016). "Germline APOBEC3B deletion is more common in East Asian women and confers a modest risk to breast cancer in both East Asian and Caucasian women." (PMID 27233495, 2016). "It has recently been shown that HER2-enriched (HER2+) breast cancers are associated with a high burden of mutations attributable to APOBEC3B." (PMID 27634334, 2016). "It has also been shown that high expression of APOBEC3B can be associated with aggressive breast cancers." (PMID 27747193, 2016). "Previous studies have shown the association of APOBEC3B for the elevated levels of DNA damage and mutation in several breast cancer cell lines." (PMID 27977754, 2016).
breast cancer (continued). "APOBEC3B mRNA knockdown caused a corresponding depletion of all measurable DNA deaminase activity in breast cancer cell line nuclear extracts." (PMID 25848704, 2015). "Haploinsufficiency for genes disrupted by a hemizygous deletion is also an important mechanism for genetic disease, such as APOBEC3B and breast cancer risk." (PMID 27600231, 2015). "Recent work has resulted in the discovery of APOBEC3B as an active, enzymatic source of mutation in breast cancer." (PMID 25848704, 2015). "The DNA cytosine deaminase APOBEC3B is a newly defined source of DNA damage and mutation in breast cancer." (PMID 25848704, 2015). "Two additional lines of evidence strongly linked APOBEC3B overexpression to breast cancer mutagenesis." (PMID 25848704, 2015). "For independent validation, APOBEC3B mRNA expression was associated with patient outcome data in five additional cohorts (over 3,500 breast cancer cases)." (PMID 25123150, 2014). "The innate immune DNA cytosine deaminase APOBEC3B was recently identified as a predominant source of context dependent cytosine base substitution mutations in breast cancer." (PMID 25123150, 2014). "Recent studies of tumors such as breast cancers and lymphomas have shown that increased expression of APOBEC3B in vivo was linked to the chronic induction of mutations and/or instability in genomic DNA." (PMID 24667791, 2014). "Genome-wide patterns of APOBEC3-catalyzed deamination in yeast reveal APOBEC3B and 3A as the deaminases whose mutational signatures are most similar to those of breast cancer kataegic mutations." (PMID 23599896, 2013). "The target-specificity data implicating APOBEC3B in the breast cancer mutation is not only supported by our demonstration that its enforced expression can yield DNA damage but also by the fact that it is well expressed in breast cancer cell lines." (PMID 23599896, 2013). "For APOBEC3A, the top ten pathways included those involved in epidermal and keratinocyte development and differentiation, whereas, consistent with observations in bulk RNA-seq data from breast cancer, all processes in the top ten for APOBEC3B were associated with mitosis (Dataset EV1)." (PMID 39548236, 2025). "It is possible that the increased expression of APOBEC3B associated with rs1014971 may contribute to breast cancer susceptibility through mutagenesis-independent mechanisms, some of which have been proposed’ as mechanisms with such a function before." (PMID 38254863, 2024). "In addition, the germline APOBEC3B deletion of ~30 kb, which extends between the last exon of APOBEC3A and the eighth exon of APOBEC3B and removes the entire APOBEC3B protein-coding region, was associated with increased breast cancer risk in Asian populations." (PMID 37510234, 2023). "APOBEC3B is a good candidate gene for breast cancer susceptibility." (PMID 37510234, 2023). "APOBEC3B (A3B) is aberrantly overexpressed in a subset of breast cancers, where it associates with advanced disease, poor prognosis, and treatment resistance, yet the causes of A3B dysregulation in breast cancer remain unclear." (PMID 37190094, 2023). "Although overexpression of APOBEC3B has been associated with the pathogenesis of breast cancer, the role of germline mutations of this gene in the etiology of breast cancer remains unclear." (PMID 37510234, 2023). "Expression of APOBEC3B is upregulated in breast cancer and it was associated with kataegis, aggressive clinical and pathological features of breast tumors, and poor prognosis among patients with estrogen receptor-positive (ER+) breast cancer." (PMID 37510234, 2023). "To investigate whether the APOBEC3B c.783delG mutation predisposes to different cancers, we reviewed the pedigrees of patients with breast cancer who carry the mutation and compared them with the pedigrees of patients without the mutation." (PMID 37510234, 2023).